CA9 (carbonic anhydrase 9)
Diseases named in the same sentence as CA9 in open-access papers (continued):
Sharing a sentence is not in itself a finding about the gene and the disease.
cancer (continued). "It was shown that CA9 knockdown inhibits tumor growth and decreases the number of cancer cells; however, the level of CA12 mRNA is up-regulated." (PMID 33321910, 2020). "Here, we confirmed that the mRNA expression of CA9 in ccRCC was significantly higher than that in para-carcinoma tissues from analysis of the datasets in The Cancer Genome Atlas." (PMID 32824856, 2020). "Studies have shown that cancer cells adapt to this acidic milieu thanks to the activity of carbonic anhydrases including CA9, which catalyzes the conversion of carbon dioxide into bicarbonate." (PMID 31013771, 2019). "First, we confirmed the mRNA and protein expression of ERO1α and CA9 in various normal and cancer cell lines under normoxic in vitro culture by qPCR and WB analyses." (PMID 31142270, 2019). "Using quantitative real-time polymerase chain reaction, we analysed the mRNA expression of ERO1α and CA9 in different normal and cancer cell lines." (PMID 31142270, 2019). "ERO1α and CA9 mRNA levels in hypoxic cultures were investigated by qPCR in various cancer cell lines." (PMID 31142270, 2019). "Silvia Pastorekova showed that CA9 ectodomain cleavage affects the cancer cell phenotype and microenvironment." (PMID 30338239, 2018). "Shonagh Russell then demonstrated that CA9 overexpression supports the glycolytic phenotype of cancer cells and increases their metastatic propensity." (PMID 30338239, 2018). "Targeting CA9, a carbonic anhydrase which detoxifies the gaseous byproducts of hypoxic metabolism, has demonstrated a potential therapeutic benefit in some cancers." (PMID 29966011, 2018). "Other soluble molecules in rinsing include MMP-11, lysyl oxidase-1 (LOX-1) and carbonic anhydrase IX (CA-9), all of which have been shown to facilitate cancer invasion in vivo." (PMID 29158312, 2018). "For example, SEZ6L2 was higher ranked than CA9 in our analysis but CA9 was selected due to the availability of molecular imaging probes targeting this marker and based on its potential applicability among several cancer types." (PMID 29371917, 2017). "In response to hypoxia in human cancer cells, carbonic anhudrase 9 (CA9) is the most strongly expressed gene." (PMID 29100431, 2017). "Several studies have suggested that CA9 variations influence the severity and prognosis of several types of cancer, including prostate cancer, urothelial cell carcinoma, and oral cancer." (PMID 29100431, 2017). "The roles of miR-34a-dependent CA9 regulation, as another level of epigenetic regulation, in cancer under hypoxia or normoxia are still worth investigating in the future." (PMID 28667334, 2017). "A recent review has emphasized the widespread expression of CA9 in human cancers and related it to both poor outcome and stem cell markers." (PMID 27901496, 2017). "A coordinative binding of HIF-1 and SP1 transcription factors is necessary for CA9 expression in oxygenated cancer cells, and lactate augments the level of expression by increasing HIF-1α availability." (PMID 29100428, 2017). "Cancer cells can regulate intra- or extracellular pH levels by carbonic anhydrase 9 (CA9) and sodium/proton exchanger 1 (NHE1) on the cell surface (number 9)." (PMID 28417928, 2017). "Similar to VEGF, hypoxia-inducible metabolic enzyme CA9 is overexpressed in cancer cells and has been proposed as a useful marker for hypoxic exposure." (PMID 27379206, 2016). "It is the membrane-bound CA9, whose expression correlates with aggressive disease and poor survival in many cancers, that is thought to modulate pH through the interaction with bicarbonate transporters on the cell surface." (PMID 27588494, 2016). "Preclinical studies in cultured cells have clearly demonstrated that CA9 stimulates the metastatic properties of cancer cells." (PMID 27478411, 2016). "To examine the behavior of cancer cells in tissue, we subcutaneously injected Ca9/K17+, Ca9, HSC3/K17- and HSC3 into the cephalic dermis of athymic mice." (PMID 27512993, 2016).
cancer (continued). "The regulated markers of HIF-1α, such as glucose transporter type 1 (GLUT1), carbonic anhydrase 9 (CA9) and c-Met, have been found to be highly associated with poor prognosis in various cancers." (PMID 25993275, 2015). "CA9 is overexpressed in a wide spectrum of human cancers, and has been proposed to be a potential intrinsic marker of hypoxia." (PMID 25789026, 2015). "Here we show that the onset of hypoxia-induced cancer stem cell features requires the beta-catenin-dependent post-transcriptional up-regulation of CA9 and SNAI2 gene expression." (PMID 24260469, 2013). "Cancer gene expression profiling studies with up-regulated CA9 (FC>2) related to significantly activated focal adhesion pathway as identified by SPIA algorithm." (PMID 24101905, 2013). "Our data show that novobiocin reduced selective HIF1α target gene mRNA, especially that of CA9 in several cancer cell lines." (PMID 23671581, 2013). "CA9 expression regulates pH in the hypoxic microenvironment to promote survival and proliferation of cancer stem cells." (PMID 24260469, 2013). "HIF-1α and its regulated markers including c-Met, CA9 and GLUT1 were reported to be highly expressed in various cancers and associated with poor prognosis." (PMID 23927384, 2013). "Carbonic anhydrase 9 (CA9) is reportedly overexpressed in several types of carcinomas and is generally considered a marker of malignancy." (PMID 23226559, 2012). "Immunohistochemistry showed strong correlation of carbonic anhydrase 9 expression (a marker of hypoxia) in primary and secondary cancers (P=0.0002)." (PMID 21540863, 2011). "As CA IX is an attractive target for anti-cancer therapy for several reasons, overexpression of CA9 is an important finding that is likely to be clinically relevant." (PMID 21910893, 2011). "In concordance with this, in the 7 gene set, TSPYL5 and CA9 have been previously used as prognostic biomarkers in cancer." (PMID 19208118, 2009). "It is also detectable in normal tissues in the absence of the full-length transcript and can therefore produce false-positive data in prognostic studies based on the detection of the hypoxia- and cancer-related CA9 expression." (PMID 18026188, 2008). "This pattern of expression resembles that of most other carcinomas with strong and membranous positivity for CA9 at the periphery of areas of necrosis." (PMID 15558070, 2005). "This is in direct contrast with the expression of CA9, where its expression was strongly related with the extent of necrosis and most often localised in cancer cell layers proximal to necrotic areas." (PMID 12942121, 2003). "In this study, we provide new mechanistic insights into CA9 regulation in malignant tumors." (PMID 41535258, 2026). "Given that dephosphorylation at Ser448 is required for full enzymatic activity, these findings suggested that formononetin may exert anti-cancer effects by disrupting CA9 enzyme function." (PMID 41567641, 2025). "CA9 inhibitors are considered a potential remedy in cancer therapy." (PMID 41516250, 2025). "In addition, cancer cells showed decreased levels of hypoxia, identified by having a lower carbonic anhydrase (CA9+) area per image view." (PMID 39905264, 2025). "Alkaliptosis induces selective cancer cell death and is regulated by CA9 and NF-κB." (PMID 41185600, 2025). "Additionally, CA9 has been correlated with several cancer stem cell (CSC) markers in numerous studies." (PMID 40873634, 2025). "CA9, another downstream gene of HIF1A, is well‐known for its association with various cancers." (PMID 40417738, 2025). "A CA9 LFA could potentially permit rapid detection of carcinoma in patients with nodules/masses of unknown etiology avoiding invasive procedures, e.g., kidney biopsies." (PMID 40723287, 2025). "CA9, a membrane associated CA isoform, is known to be induced by hypoxia, involved in adaptation to acidosis and implicated in cancer progression via its catalytic and/or non-catalytic functions." (PMID 38530845, 2024).
cancer (continued). "In ccRCC group, cancer cells were annotated by their significant expression of CA9, CTR2, NDUFA4L2." (PMID 38872260, 2024). "CA9, best known for its diverse roles in cancer, is a promising therapeutic target." (PMID 39768175, 2024). "Its limited expression in healthy tissue makes CA9 a promising cancer treatment target." (PMID 39768175, 2024). "CA9 is a hypoxia-inducible protein that is involved in pH regulation in hypoxic cancer cells." (PMID 38473425, 2024). "However, CA9 was dominating in the cancer cell lines, whereas LOX and LOXL2 were dominating in the fibroblasts." (PMID 39011470, 2024). "Notably, the cancer-related genes CA9 and NDUFA4L2 and the epithelial marker genes KRT8 and EPCAM were expressed across cell states 1, 2, 3, and 5, and before the second differentiation node, marking the presence of TECs." (PMID 39301023, 2024). "Annotation of cancer cell clusters in scRNA data with corresponding clusters in scATAC data revealed that the three meta programs manifested elevated expression and chromatin opening of cancer-specific markers (CA9 and NDUFA4L2)." (PMID 38944814, 2024). "The exterior cellular acidity of CA9 has a supportive effect on carcinoma cells." (PMID 38561760, 2024). "CA9 may potentially affect the endocytosis of transferrin, thus affecting iron uptake by cancer cells." (PMID 36760347, 2023). "The pharmacological blockage of HIF or CA9 with specific inhibitors to transform the cold immune environment of such HIF-driven tumors could eventually have therapeutic implications in cancer immunotherapy." (PMID 35735451, 2022). "CA9 is an endogenous marker for hypoxic cells and regulates pH in hypoxic cancer cells." (PMID 35625561, 2022). "Carbonic anhydrase 9 (CAIX) is involved in cancer angiogenesis under hypoxia." (PMID 36483049, 2022). "Additionally, the preservation of low pH in TME is also aided by carbonic anhydrase 9 (CA9), which is overexpressed in several cancer types." (PMID 36568636, 2022). "CA9 is also a marker for poor clinical outcome in most cancer types." (PMID 35440019, 2022). "Furthermore, CA9 has a drug targeting role due to its low expression in normal tissues and increased expression in several cancer tissues, including lung, colorectal, oral, uterine, renal and bladder cancer." (PMID 36415514, 2022). "In CRC, CA9 showed heavier expression in carcinomas than in benign lesions." (PMID 35440019, 2022). "Recent evidence shows that the enzyme activity of CA9 and the related acidic microenvironment not only play a key role in the survival of cancer cells under hypoxia and their migration and invasion characteristics, but also play a key role in immune surveillance." (PMID 35155218, 2021). "The specific effects of 887S and 887L on CA9 among CA family members indicate that targeting upstream molecules may offer a suitable alternative option for CA9-based anti-cancer drug design." (PMID 34493285, 2021). "CA9 expression of cancer cell subgroup is related to CD8+ T cell infiltration." (PMID 35155218, 2021). "Carbonic anhydrase 9 (CA9/CAIX) was a specific anoxic biomarker that was expressed in many cancers." (PMID 33815132, 2021). "Since CA9 is almost exclusively expressed in cancer cells, it might function as promising biomarker and therapeutic target." (PMID 33276608, 2020). "In addition to low normal tissue distribution and upregulation in cancer, CA9 as a potential theranostic target has several other key advantages." (PMID 33007872, 2020). "CA9 plays a direct role in stimulating an adaptive immune response, and the inhibition of CA9 reduces the capacity of cancer cells to acidify the extracellular environment, which could lead to enhanced immune activity." (PMID 32181755, 2020). "By its catalytic function, CA9 is involved in cancer cell migration and invasion." (PMID 33276608, 2020).
cancer (continued). "Notably, the GAG-modified version of CA9 (PG-CA9) showed an impaired internalization in cancer cells due to translocation of PG-CA9 to caveolin-1 enriched membrane regions." (PMID 30767150, 2019). "Thus, the involvement of bicarbonate transporters and associated enzymes, such as CA9 and CA12, provides favorable condition to facilitate cancer progression as well as motility." (PMID 31546841, 2019). "In addition to V-ATPase, other proton extruders have been associated with cancer, like Na+/H+ exchanger (NHE), monocarboxylate transporters (MCT), and carbonic anhydrase 9 (CAIX)." (PMID 30825056, 2019). "Based on these observations, we hypothesized that the malignant phenotypes of cancer cells are further exaggerated by CA9 expression in younger individuals with DGC." (PMID 30034621, 2018). "Despite the molecular and cellular functions of CA9 being well-characterized, the impacts of its gene polymorphism in cancer incidence and progression are not fully understand." (PMID 28667334, 2017). "Confirmation that CA9 contributes to the control of pHi regulation in addition to acidification of pHe prompted a widespread effort to develop pharmacological agents to target this almost exclusive cancer protein." (PMID 28055960, 2017). "In this context, monocarboxylate transporters (MCTs), responsible for lactate transport, their chaperones CD147 and CD44, as well as the glucose transporter 1 (GLUT1) and the pH regulator carbonic anhydrase 9 (CAIX) arise as key players in the metabolic reprogramming of cancer cells." (PMID 28969033, 2017). "This suggests that genetic variations of CA9 may also induce differences in the incidence risks and outcomes of cancers." (PMID 28667334, 2017). "Furthermore, for all the models, the cancer-initiating potential appears to reside primarily in the CA9 positive fraction." (PMID 27901496, 2017). "CA9 is a well-known hypoxic indicator and plays an important role in maintaining the intracellular pH despite increased extracellular acidosis, thereby promoting cancer cell survival and growth in hypoxic-acidic environments." (PMID 26156831, 2015). "CA9 expression is often upregulated in cancer cells in response to hypoxic-acidic environments." (PMID 26156831, 2015). "CA9-specific small molecule inhibitors restricted the expansion of cancer stem cells." (PMID 26156831, 2015). "The expression of Ca9 is strongly induced by hypoxia in many human cancers." (PMID 21966417, 2011). "It is unclear whether CA9 was secreted by the cancer cells or whether it was released from damaged cancer cells." (PMID 18841153, 2008). "Poorly differentiated carcinomas were associated with nuclear HIF-1α and membranous CA9 expression." (PMID 15558070, 2005). "We speculate that this CA9 LFA has potential for screening of more common cancers." (PMID 40723287, 2025). "Furthermore, considering that U-104 has been reported to enhance the effectiveness of chemotherapeutic drugs in killing cancer cells, we wondered whether CA9 inhibition could improve the cisplatin sensitivity of NB cells." (PMID 38177154, 2024). "However, little is known about the miRNA-dependent regulation of CA9 expression in cancer." (PMID 28667334, 2017). "To further explore the dysadherin/CA9 axis in CRC, we analyzed CA9 expression in cancer (GSE21510) and stratified 156 CRC patient samples into high- and low-CA9 expression groups on the basis of the median expression value." (PMID 41535258, 2026). "Two targets, CA9 and MME, were consistently identified across all three analyses, suggesting their central roles in formononetin-mediated anti-cancer effects." (PMID 41567641, 2025). "An extracellular acidic environment and an intracellular mildly alkaline environment induced by carbonic anhydrase 9 (CA9) play a critical role in self‐renewal, invasion, migration, and drug resistance of cancer stem cells (CSCs) within hypoxic solid tumors." (PMID 40873634, 2025).
cancer (continued). "We noted abundant expression of the hypoxia-related marker CA9 in the HT-29 and SW480 cancer cell monocultures and heterospheroids, whereas the fibroblasts expressed a low level." (PMID 39011470, 2024). "We selected three HIF-1α downstream genes (GLUT-1, CA9 and VEGF) since their overexpression is known to contribute to cancer progression through various mechanisms including metabolism reprogramming (for GLUT-1 and CA9) and angiogenesis (for VEGF)." (PMID 39458615, 2024). "The crucial roles of CA9 and CA12 in intracellular pH maintenance represent the means by which cancer cells adapt to the toxic conditions of the extracellular milieu." (PMID 35362480, 2022). "This increase in energy supply contributes to metastasis and is also facilitated by the stimulation of EMT, the invasion of cancer cells (BHLHE41), the development of acidosis (CA9), and an improvement in angiogenesis (VWF)." (PMID 34046336, 2021). "The addition of benign cell lysate resulted in a significant increase of MMP9, VEGFA, ApoE, ANG, and MMP10, and the addition of cancer cell lysate resulted in a significant increase of MMP9, CA9, PAI1, ApoE, A1AT, ANG, and MMP10." (PMID 34204951, 2021). "We further performed double staining for CA9 and FOXP3 on 20 selected cases that expressed CA9 in 30–60% of the cancer cell population, containing areas with positive expression and lack of expression." (PMID 32066909, 2020). "Surprisingly, both CA9 and WNT7B are downregulated in HCC, most so in stage-I, contrary to their role in other cancers." (PMID 31277598, 2019). "Some studies, however, indicate that the expression of CA9 and GLUT-1 varies in different cancer cell lines." (PMID 31142270, 2019). "Holger M Becker further explained that CA9 increases the transport activity of MCT1 and MCT4 through direct interaction, thus facilitating lactate efflux from hypoxic cancer cells and extracellular acidosis." (PMID 30338239, 2018). "Patients with advanced cancer stages (BCLC and ALBI score) had hid significant higher levels of CA9 in the serum." (PMID 30011326, 2018). "Molecular method was based on the analysis of selected genes expression related to hypoxia (HIF1A, ANGPTL4, TGFB1, VEGFA, ERBB3, CA9) or specific for inflammation in hypoxic sites (CCL2, CCL5) at various time points after CT26 cancer cells inoculation." (PMID 30412628, 2018). "This indicates that the genetic variation at rs1048638 of the CA9 3′UTR plays an important role in regulating CA9 expression and cancer progression of HCCs, which is a novel determinant and target for HCC metastasis and prognosis." (PMID 28667334, 2017). "In conclusion, genetic variations of the CA9 3′UTR play important roles in regulating CA9 expression and cancer progression, which is a novel determinant and target for HCC metastasis and prognosis." (PMID 28667334, 2017). "The cancer pathway finder PCR array revealed 9 genes, including ACSL4, BIRC3,CA9, CCL2, FLT1, FOXC2, G6PD, IGFBP3 and SNAI2, with significantly altered expression in the siRNA-treated MCF-7 cells." (PMID 27478411, 2016). "The evidence for these molecules as reliable markers of hypoxia has been reviewed elsewhere and the overexpression of HIF-1α, CA9, GLUT1 and VEGF in various malignant tumors has also been demonstrated." (PMID 25789026, 2015). "We examined expression of HIF-1α, c-Met, CA9, and GLUT1 in cervical neoplasias and cancer specimens by IHC." (PMID 23927384, 2013). "Under conditions of hypoxia in many cancers, HIF-1α cannot be degraded and increases in the nucleus, leading to the upregulation of many hypoxia-response proteins, such as VEGF or EG-VEGF and carbonic anhydrase 9 (CA9)." (PMID 15558070, 2005). "Among these proteins, MME, CDH1, APC, and CA9 have not been previously reported to be involved in anti-cancer regulations." (PMID 41567641, 2025).